CRP (C-reactive protein)
Diseases named in the same sentence as CRP in open-access papers (continued):
Sharing a sentence is not in itself a finding about the gene and the disease.
pneumonia (continued). "When physicians, after taking history and physical exam, are in doubt whether pneumonia is present and prescription of antibiotic treatment is indicated or not, measuring the C-reactive protein concentration and using the decision rule may be helpful in clinical practice." (PMID 21569472, 2011). "According to this tree, patients with C-reactive protein of below 10 μg/ml or patients presenting with C-reactive protein between 11 and 50 μg/ml, but without dyspnea and without daily fever can be classified as non-pneumonia cases and a prescription of antibiotics is not necessary." (PMID 21569472, 2011). "Patients with pneumonia in thesevere group exhibited high levels of white blood cells (WBCs), neutrophil, NLR,hs-CRP, and PCT compared to the non-severe group (P <0.05)." (PMID 40990897, 2025). "Scholars have found that compared with CRP and PCT, ProADM is more valuable in evaluating the severity of pneumonia in children, which is attributed to ProADM not relying on different types of pathogic infection." (PMID 39411281, 2024). "There are many laboratory indicators for evaluating the severity of pneumonia, such as WBC, ESR, CRP, interleukin (IL), etc., but there is no specificity." (PMID 38822291, 2024). "In this study, CRP and PCT were significantly elevated in pneumonia cases compared to controls, but they were neither good severity indicators nor prognosticators of death." (PMID 36963048, 2023). "We identified 227 patients in the study group with fever, hypothermia, and/or elevated C-reactive protein (CRP) but no respiratory symptoms or signs, and estimated ULDCT and CXR sensitivity and specificity in detecting pneumonia." (PMID 37115214, 2023). "CRP by itself was more reliable than other laboratory values (PCT, OPN, Neu, and purulent sputum) in identifying pneumonia in AECOPD, independent of current treatment of ICS and SCS, indicating that CRP maintains the major role in this regard." (PMID 35400078, 2022). "Chest radiography, elevated C reactive protein, white blood cell and neutrophil counts were not useful to predict death or ICU admission in children hospitalized with pneumonia." (PMID 34388194, 2021). "In contrast, the NLR was not comparable to CRP and PCT for diagnosing or evaluating the severity of pneumonia in recently published study." (PMID 33857241, 2021). "We found that individuals with a previous history of pneumonia presented increased TC, LDL-C, non-HDL-C, CRP levels, and decreased creatinine." (PMID 33149723, 2020). "The proportions of ARDS, a high C-reactive protein (CRP) level and an abnormal paO2/FiO2 ratio were higher in patients with than without pneumonia, as expected." (PMID 33287847, 2020). "CRP and WBC remain important indicators of pneumonia, and according to our findings, pneumonia should be treated as a bacterial disease regardless of the virus findings." (PMID 30991957, 2019). "The differences between the levels of CRP in non-severe, H1N1-pneumonia and H1N1-hospitalization/death subgroups were statistically significant (p < 0.05)." (PMID 30288556, 2019). "In contrast, C-reactive protein (CRP) levels and white blood cell counts did not significantly differ by pneumonia severity in younger and elderly patients." (PMID 30616612, 2019). "In a large study investigating the accuracy of a clinical prediction model for the presence of pneumonia, AUROC was 0.70 without, and 0.77 with the addition of C-reactive protein." (PMID 30991716, 2019). "Among traditional biomarkers, two host protein assays based on C-reactive protein (CRP) and procalcitonin (PCT) are widely used in pneumonia diagnosis, with PCT being more sensitive to bacterial/non-bacterial cases and for evaluating severity." (PMID 31316955, 2019). "In our analysis, pneumonia patients had higher WBC counts and CRP levels than non-pneumonia patients." (PMID 31370781, 2019).
pneumonia (continued). "The CRP, WCC and ANC did not vary significantly between presumed viral and other pneumonia cases and between empyema and bacteraemia cases." (PMID 30940126, 2019). "Applying a cut‐off value of CRP at 20 mg/l, the negative likelihood ratio for either a positive blood or urine culture or IMCI pneumonia was 0.71 (95% CI 0.57–0.87)." (PMID 27935664, 2017). "Significantly increased pneumonia severity index (PSI), respiratory rate, and lower PaO2/FiO2, hypersensitive CRP were reported in non-survivors compared to survivors (P = 0.013, 0.022, 0.019 and 0.026, respectively)." (PMID 26967644, 2016). "Median CRP and PCT levels were higher in hypoxemic compared with non-hypoxemic pneumonia cases (P = 0.03 and P = 0.007, respectively)." (PMID 26696249, 2015). "Plasma levels of CRP, PCT, and CHI3L1 were elevated in end-point pneumonia compared to non-end-point pneumonia and significant in ROC curve analysis." (PMID 26366571, 2015). "AUCROC analysis showed that PTX3 levels in BAL fluid predicted pneumonia (AUCROC =0.815, 95% CI =0.710 to 0.921, P <0.0001), whereas BAL fluid levels of sTREM-1, plasma PTX3, sTREM-1, CRP and PCT did not." (PMID 25314919, 2014). "PLT was correlated with CRP and ESR values in the tuberculosis group (r = 0.57, r = 0.56, p < 0.001; respectively), while it was not correlated with CRP and ESR in the pneumonia group (r = 0.20, r = 0.26, p > 0.05, respectively)." (PMID 23114411, 2012). "The adult patients with pneumonia had higher leukocytes counts, CRP and ESR values with lower lymphocyte differentials than the adults without pneumonia." (PMID 22443897, 2012). "PLT was correlated with CRP and ESR values in the tuberculosis group, while it was not in the pneumonia group." (PMID 23114411, 2012). "PLT was positively correlated with CRP and ESR values in the tuberculosis group (p < 0.001), while it was not correlated with CRP and ESR in the pneumonia group (p > 0.05)." (PMID 23114411, 2012). "Patients with pandemic (H1N1) 2009 influenza CAP differed significantly from those without pneumonia regarding length of stay, need for ICU admission, CRP and the likelihood of disabling sequelae." (PMID 20877727, 2010). "Since the CRP levels and WBC count were significantly elevated, regardless of the bacterial test results, five pneumonia patients were treated with empirical antibiotics prior to admission, seven patients were treated with empirical antibiotics during hospitalization." (PMID 40346698, 2025). "The severe pneumonia group had significantly higher age, CCI score, heart rate, respiratory rate, temperature, white blood cell count, C-reactive protein, procalcitonin, blood urea nitrogen, creatinine, lactate, and SOFA score than the non-severe pneumonia group." (PMID 38887257, 2024). "ROC curve analysis revealed that C-reactive protein (CRP) levels could distinguish patients with AE-COPD with and without pneumonia (AUC = 0.78)." (PMID 38910264, 2024). "Nonspecific biomarkers, such as C-reactive protein (CRP) and procalcitonin, are valuable for assessing the severity of the disease and response to treatment in patients with pneumonia; however, it remains a challenge to distinguish between bacterial and viral infections." (PMID 37189569, 2023). "In addition to the biomarkers that were associated with the development of hypoxemia (IFN-α, IL-6, CXCL10, LDH, and CRP), VEGF, NLR, and adjusted NT levels were significantly higher in patients with pneumonia than in those without pneumonia." (PMID 37731495, 2023). "In contrast, CRP levels were elevated in patients with pulmonary infiltrates, hence an increase in CRP levels might indicate a non-VAD infection, e.g., pneumonia." (PMID 37899422, 2023). "Interestingly, decreased CASC2 levels showed a negative correlation with the levels of CRP, IL‐6, PCT, and D‐dimer in children with severe pneumonia." (PMID 35665444, 2022).
pneumonia (continued). "In patients having pneumonia with unknown etiology, the FCBI-index and CRP values (but nor PCT values) were statistically significantly increased when compared to patients with non-pneumonic viral RTIs and pneumonic influenza A virus infection." (PMID 34844193, 2021). "The median values of CRP were 62.7 mg.L-1 [38.5–107.5] and 100.7 mg.L-1 [59.0–205.2] (p = 0.001), and of PCT 0.2 μg.L-1 [0.1–0.7] and 0.4 μg.L-1 [0.1–1.9] (p<0.05) in patients with and without pneumonia, respectively." (PMID 32997689, 2020). "In patients with community-acquired pneumonia (CAP), the plasma concentration of PTX3, but not CRP, was correlated with the severity of CAP based on the pneumonia severity index (PSI), CURB-65, Acute Physiology and Chronic Health Evaluation (APACHE) II scores, and the length of hospital stay." (PMID 25530683, 2014). "Compared with the group without pneumonia, the males were over-represented in the pneumonia group (P = 0.001) and longer hospitalizations (P < 0.001), higher values for hemoglobin (P = 0.03), WBC (P < 0.001) and CRP (P < 0.001) and lower values for lymphocyte differential (P < 0.001)." (PMID 21864391, 2011). "CRP has been shown to be a reliable biomarker for COPD in systemic inflammation responses and cardiovascular events, however, it is not good marker for predicting pneumonia in COPD patients with ICS treatment." (PMID 21962211, 2011). "The progression from pneumonia to septic shock showed a significant increase in APACHE III and MOF scores as well in levels of leucocytes, although there was no significant increase in the levels of C-reactive protein, lactate and platelets." (PMID 16280065, 2005). "Procalcitonin and CRP were equally useful in children infected and not infected with HIV to improve the specificity of the pneumococcal pneumonia efficacy endpoint in the vaccine trial among children with CXR-confirmed pneumonia." (PMID 15736995, 2005). "In this study, we analyzed the difference of clinical features between pneumonia and non-pneumonia among AFRI patients in fever clinics and developed a DRC model comprised of three items, including dyspnea, respiration rates > 20 /min, and CRP > 20 mg/l, for pneumonia prediction." (PMID 36253753, 2022). "Patients with pneumonia but without progression to acute respiratory distress syndrome (ARDS) maintained HLA-DR expression in monocytes with vivid antigen presentation, a moderate elevation of C-reactive protein (CRP), d-dimer and alanine transaminase (ALT)/aspartate transaminase (AST)." (PMID 36289881, 2022). "Of note, respiratory rate, blood pressure, pulse, haemoglobin, c-reactive protein (CRP), prothrombin time (PT), activated partial thromboplastin time (APTT), and albumin were found to have significant differences between the patients with or without pneumonia (P < 0.05)." (PMID 36684357, 2022). "The CRP, a non-specific marker of inflammation, may be elevated due to a sustained immune response from HIV infection itself, or due to co-infections, such as TB or pneumonia." (PMID 35725387, 2022). "CRP can be used to monitor inflammation but might not represent the most accurate marker to discriminate between the severity of the respiratory and systemic inflammatory involvement during SARS-CoV-2-related pneumonia." (PMID 33753759, 2021). "While CRP ≥40 mg/L may be a fairly specific marker to rule out most RSV pneumonias (83% of RSV pneumonia cases had CRP <40 mg/L), it had inadequate sensitivity as 23% of cases with confirmed bacterial severe or very severe pneumonia also had CRP <40 mg/L." (PMID 28575375, 2017).
type 2 diabetes (885 papers, 2005 to 2026). "BMI, type 2 diabetes, C-reactive protein, and decompensated OSAS were independently associated with TT (P = .039; P = .006, P = .003, and P = .014, respectively)." (PMID 41284733, 2026). "Elevated CRP, even within high-normal ranges, has been independently linked to increased risk of cardiovascular events, type 2 diabetes, and all-cause mortality, making it a clinically actionable marker even in asymptomatic individuals." (PMID 41465826, 2025). "For instance, by using variants in the FTO locus as instruments and plasma CRP level as the proxy exposure, the authors inferred a putative causal link between altered FTO function (proxied by variant effect on CRP) and type 2 diabetes risk." (PMID 41004399, 2025). "C-reactive protein (CRP), an acute-phase protein indicative of systemic inflammation, has also been positively associated with the risk of type 2 diabetes, cardiovascular disease, and both cardiovascular and all-cause mortality." (PMID 41222611, 2025). "We compared the triglyceride–glucose–neutrophil-to-lymphocyte ratio (TyG-NLR) and a C-reactive protein–TyG–based index (CTI) to examine their associations with severity outcomes in hospitalized adults with type 2 diabetes." (PMID 41458543, 2025). "Diets rich in flavonoids have been associated with decreased levels of CRP and lipid peroxidation in individuals with type 2 diabetes and nephropathy." (PMID 41011276, 2025). "A modest increase in CRP, a marker of inflammation associated with type II diabetes and cardiovascular disease in particular, was observed only in females, aligning with clinical data showing higher CRP levels in women across health and disease states." (PMID 41327907, 2025). "This inflammatory response extends beyond adipose tissue, leading to systemic inflammation characterized by elevated levels of C-reactive protein (CRP), which accelerates IR progression and increases type 2 diabetes risk." (PMID 40438499, 2025). "Smoking also triggers inflammatory responses, as shown by elevated C-reactive protein levels in smokers, a factor linked to type 2 diabetes." (PMID 40966607, 2025). "A meta-analysis of multiple single-berry interventions in clinical trials reported significant reductions in CRP (hs- and standard assay) across healthy adults, those with metabolic syndrome and type 2 diabetes, and those with cardiovascular risk factors." (PMID 38999806, 2024). "Certain indicators such fibrinogen, C-reactive protein, and white blood cell count (CRP) have beeninvestigated as possible indicators of type 2 diabetes developments, as seen in studies like Atherosclerosis Risk and Communities." (PMID 39132231, 2024). "An observational study recently found an increased risk of vascular mortality in patients with type 2 diabetes and with CRP concentrations of 3.2–10 mg/L." (PMID 38730445, 2024). "Currently, the most commonly used inflammatory marker for predicting the risk of type 2 diabetes is high-sensitivity C-reactive protein (hsCRP)/CRP." (PMID 38281997, 2024). "There has been some evidence showing that certain cardio-metabolic traits such as obesity, type 2 diabetes, and C-reactive protein levels are associated with an increased risk of infectious complications." (PMID 38459230, 2024). "Type II diabetes, lipid traits, and C-reactive protein showed low polygenicity (<2,500 causal risk variants)." (PMID 37693619, 2024). "The cumulative incidence of type 2 diabetes stratified by plasma CRP showed a gradually increasing risk of type 2 diabetes from age 40 in individuals with CRP ≥ 2 mg/L compared to CRP < 2 mg/L (d)." (PMID 38730445, 2024). "In adults with type 2 diabetes, better diet quality (i.e., more plant-based foods and less processed foods) was significantly associated with lower standard assay CRP concentrations in males and females across five ethnic groups." (PMID 38999806, 2024).
type 2 diabetes (continued). "To address the independent associations between the coagulation factors and incident type 2 diabetes, we adjusted the associations for inflammation marker, CRP." (PMID 39404973, 2024). "CRP is an inflammatory biomarker that can indicate inflammation in the body associated with various conditions, including type 2 diabetes." (PMID 39091901, 2024). "Further novel findings indicate a higher prevalence of type 2 diabetes (C-peptide), inflammation (C-Reactive Protein), vitamin deficiency (homocysteine, methylmalonic acid), and inflammatory arthritis." (PMID 37085506, 2023). "A GRS for lower FEV1 was most strongly associated with increased risk of asthma and COPD, family history of chronic bronchitis/emphysema, lower hand grip strength, increased fat mass, increased HbA1c and type 2 diabetes risk, and elevated C-reactive protein." (PMID 36914875, 2023). "A longitudinal study following up for 10 years showed that higher levels of inflammatory markers such as serum interleukin-6 (IL-6) and C reactive proteins (CRP) were associated with subsequent cognitive decline in older adults with type 2 diabetes." (PMID 37213540, 2023). "Firstly, nut consumption has been reported to be associated with improved inflammatory status, including C-reactive protein, interleukin-6, and fibrinogen, and thus reduce risk of cardiovascular disease and type 2 diabetes." (PMID 36570151, 2022). "For example, an increase in C-reactive protein (CRP) previously associated with low SWB is a strong independent predictor of Type 2 diabetes." (PMID 36418961, 2022). "Semaglutide is a GLP-1 analogue that reduces CRP concentrations and reduces cardiovascular risk in people with type 2 diabetes." (PMID 36467859, 2022). "Epigenetic associations between SOCS3-cg18181703 and C-reactive protein, inflammatory bowel disease, type-2 diabetes and cognitive abilities also suggest potential pleiotropic effects of SOCS3 gene." (PMID 36303554, 2022). "The KORA S4/F4 study showed that biomarkers of subclinical inflammation, such as high-sensitivity C-reactive protein and serum amyloid A, were independently associated with 7-year changes in HbA1c before the diagnosis of type 2 diabetes." (PMID 35436969, 2022). "Higher baseline levels of inflammatory markers, including plasma IL-6, fibrinogen and C-reactive protein, were associated with subsequent cognitive decline in older people with type 2 diabetes." (PMID 34932135, 2022). "Regarding the other SNPs in this haplotype, functional consequences identified to date include associations with plasma CRP and fibrinogen, osteoporosis, age of menarche, fasting glucose levels, early onset type II diabetes mellitus, and cancer." (PMID 34421692, 2021). "RA occurrence, AS occurrence, type 2 diabetes occurrence and a higher C-reactive protein concentration can be independently associated with a higher probability of non-ischemic left ventricular myocardium injury." (PMID 34173901, 2021). "In AMV analyses in prospective cohorts, glycoprotein acetyls were positively associated with cardiovascular diseases and type 2 diabetes, independently of established risk factors and CRP." (PMID 33731105, 2021). "Elevated levels of IL-6 and CRP are strongly associated with development of type 2 diabetes in healthy middle-aged women." (PMID 34867458, 2021). "In fact, a higher fiber intake (≥15 g/1,000 kcal) was associated with lower HbA1c and CRP than lower fiber intake in 1,785 middle-aged people with type 2 diabetes." (PMID 34055004, 2021). "In the same group, the occurrence of RA, the presence of AS, the occurrence of type 2 diabetes and a higher CRP can be independently associated with a higher probability of non-ischemic injury to left ventricular myocardium." (PMID 34173901, 2021). "We also sought to determine if serum PCT correlated better than CRP with cardiovascular risk in these patients with type 2 diabetes." (PMID 34725609, 2021).